MTOR (mechanistic target of rapamycin kinase)
Diseases named in the same sentence as MTOR in open-access papers (continued):
Sharing a sentence is not in itself a finding about the gene and the disease.
gastric cancer (continued). "Previous studies have shown that the PI3K/AKT/mTOR pathway regulates multiple cellular processes and plays a key role in gastric cancer progression." (PMID 39524138, 2024). "In vitro testing was conducted using SGC-7901 gastric cancer cell lines treated with p-Akt and p-mTOR inhibitors to determine the relationship between the Akt/mTOR pathway and VEGF-C/-D." (PMID 39409942, 2024). "It has been demonstrated that the PI3K/AKT/mTOR signaling pathway play an important role in cell proliferation, migration, and invasion in several cancers, including breast and gastric cancers." (PMID 39524138, 2024). "Li et al21 elaborated that S100A10 is markedly upregulated in gastric cancer and activates the mTOR pathway by interacting with annexin A2 to accelerate tumor glycolysis, thereby promoting malignant cell proliferation while suppressing apoptosis." (PMID 39128058, 2024). "Studies have shown that E2F2 regulates autophagy through the PI3K/Akt/mTOR pathway, which in turn affects the migration of gastric cancer cells." (PMID 38668684, 2024). "Procollagen-lysine,2-oxoglutarate 5-dioxygenase 1 can facilitate cell growth and aerobic glycolysis through activating the PI3K/Akt/mTOR signaling in gastric cancer cells." (PMID 39511483, 2024). "For instance, a recent study found that the flavonoid apigetrin induces autophagic cell death in AGS human gastric cancer cells through the PI3K/AKT/mTOR pathway." (PMID 39273132, 2024). "Another study mentioned that MAOA can interact with NDRG1, inhibiting downstream PI3K/AKT/mTOR pathway activity, thereby attenuating the Warburg effect in gastric cancer cells and ultimately suppressing tumor cell proliferation and malignant behavior." (PMID 39010072, 2024). "Our study found that the proteins p-PI3K, p-AKT, and p-mTOR were highly expressed in DDP-resistant gastric cancer." (PMID 38345573, 2024). "Subsequently, we used molecular docking and Western blotting to confirm that gypenosides inhibited the PI3K/AKT/mTOR signaling pathway to induce apoptosis in gastric cancer cells." (PMID 38482051, 2024). "The HMGB1/RAGE axis regulates gastric cancer cell proliferation through the Akt/mTOR and ERK signaling pathways." (PMID 38529373, 2024). "While interventions in the PI3K/Akt/mTOR pathway are well-documented, studies on other pathways in gastric cancer are limited." (PMID 39906672, 2024). "Nek2, a member of the same family as Nek6, was reported to inhibit autophagy in gastric cancer via activating protein kinase B (Akt)/mammalian target of rapamycin (mTOR) signaling pathway." (PMID 39702325, 2024). "Then, NFkB promoted the transcription of PI3KA and initiated the PI3KA/AKT/mTOR pathway to promote gastric cancer cell proliferation, migration, and invasion." (PMID 36898991, 2023). "Combining RAD001 with Rhein lowered tumor weight and volume, inhibited p-PI3K, p-Akt, and p-mTOR levels, and repressed Ki-67 expression, exerting synergistic cancer prevention in gastric cancer in vivo." (PMID 36829987, 2023). "FGFR2 promotes gastric cancer progression by downregulating thrombospondin‐4 (TSP4) through the PI3K/AKT/mTOR signaling axis." (PMID 37750089, 2023). "Ultimately, their study showed that the novel protein inhibits gastric cancer progression by regulating autophagy in gastric cancer cells through the PI3K/Akt/mTOR signaling pathway." (PMID 37829278, 2023). "In gastric cancer, exposure to Temsirolimus, an mTOR inhibitor, eradicates 5FU‐tolerant cancer cells through inhibition of the ALDH1A—mTOR axis." (PMID 37638338, 2023). "It is evidence that, PI3K/Akt/mTOR pathway targets non-small cell lung cancer, also affects breast and gastric cancer." (PMID 36849137, 2023). "An alternative therapeutic approach related to gastric cancer involves targeting dysregulated proteins within the mTOR pathway." (PMID 38001739, 2023). "PLOD1 has been shown to promote cell growth and aerobic glycolysis by regulating the SOX9/PI3K/Akt/mTOR signaling pathway in gastric cancer." (PMID 37391802, 2023).
gastric cancer (continued). "Our results suggested that YWHAH can promote the proliferation of gastric cancer cells by activating the HMGA1/PI3K/AKT/mTOR signaling pathway through Fra-1." (PMID 37415737, 2023). "It has been observed that the Notch and mTOR signaling pathways are frequently activated in human stomach cancer, which contributes to the proliferation of cells." (PMID 36733672, 2023). "Myricetin inhibits the PI3K/Akt/mTOR pathway, which lowers the rate of survival of gastric cancer cells." (PMID 37298616, 2023). "Other reports suggest that G9a promotes cell proliferation in gastric cancer and suppresses autophagy by activating mTOR." (PMID 36690274, 2023). "Using the transcriptome data of gastric cancer in our study, relevant proteins of mTOR signaling pathway were screened to identify key genes by four machine learning models, and the models were validated in external datasets." (PMID 37341987, 2023). "As an oncogene related to Lauren classification, LMOD1 modulates gastric cancer cell metastasis via the FAK-AKT/mTOR pathway." (PMID 37963970, 2023). "Knockdown of TTK inhibited proliferation and increased apoptosis of gastric cancer cells through the Akt-mTOR pathway." (PMID 37815894, 2023). "A recent trial showed the addition of mTOR inhibitors to HER2-transtuzumab-resistant gastric cancer cell lines displayed considerable cell inhibition." (PMID 37877107, 2023). "There are two pathways by which lncRNA HAGLROS regulates the mTOR signaling pathway in gastric cancer." (PMID 37313458, 2023). "It was also found that proanthocyanidins B2 can also increase caspase-3 or caspase-9 in gastric cancer cells, thereby increasing tumor cell apoptosis, reducing the expression of related proteins through the Akt/mammalian target of rapamycin (Akt/mTOR) pathway." (PMID 37237870, 2023). "In gastric cancer, DDX5 contributes to the evolution of gastric cancer cells mediating the mTOR signaling pathway activation." (PMID 36996491, 2023). "S100A10 has been shown to increase the malignant growth of cancer cells by activating the mTOR signaling pathway in osteosarcoma, gastric cancer, pancreatic ductal adenocarcinoma (PDAC), and HCC." (PMID 37892132, 2023). "Our data showed that BAP31 knockdown in gastric cancer cells was accompanied by the suppression of the PI3K/Akt/mTOR pathway, and VH-F12 induced a similar effect as BAP31 knockdown with respect to this pathway." (PMID 37834237, 2023). "AMPK/mTOR-mediated inhibition of survivin has been suggested to partially contribute to metformin-induced apoptosis in gastric cancer cells." (PMID 37835462, 2023). "Inhibition of mTOR with RAD001 in cisplatin-resistant gastric cancer cells has also yielded promising results." (PMID 36969070, 2023). "The knockout of HER2 inhibits the expression of the Akt–mTOR pathway and PD‐L1 gene and effectively increases the sensitivity of gastric cancer organoid tumors to anti‐PD‐1 therapy in vitro." (PMID 38045830, 2023). "It regulates cell proliferation, migration and invasion within gastric cancer cells while activating the PI3K/Akt/mTOR signaling pathway which often becomes dysregulated during cancer progression." (PMID 37508488, 2023). "To further confirm that YWHAH promotes gastric cancer cells proliferation by activating the PI3K/AKT/mTOR signaling pathway, we used rapamycin, an inhibitor of the PI3K/AKT/mTOR signaling pathway to treat gastric cancer cells." (PMID 37415737, 2023). "Previous studies have shown that blocking PI3K/mTOR significantly inhibits various cancers, including gastric cancer, colorectal cancer, cervical cancer, and more." (PMID 37847178, 2023). "Some kinases (e.g. PRKACA, CSNK2A1 and MAPK1) were found specifically dysregulated across multiple tumour types, but more than half were dysregulated in just one tissue (68%) such as MYLK kinase in stomach cancer and MTOR in kidney cancer." (PMID 36688815, 2023).
gastric cancer (continued). "ANXA2 interacts with S100A10 in gastric cancer to activate the mTOR pathway and inhibit apoptosis in gastric cancer cells." (PMID 37420211, 2023). "m6A‐dependent miR‐17‐92 cluster biogenesis activated the mTOR pathway, accelerating mTOR inhibitor everolimus sensitivity in gastric cancer." (PMID 36162823, 2023). "Apoptosis and autophagy were induced as a result of myricetin inhibition of the PI3K/Akt/mTOR pathway, which also reduced the survival rate of gastric cancer cells." (PMID 37298616, 2023). "ROS, also as a second messenger, can activate tyrosine kinases and MAPK which promote cell development, and the protein kinase-B (Akt)/mTOR signaling pathway which promotes cell growth of gastric cancer." (PMID 37143652, 2023). "As a result, myricetin appears to inhibit the PI3K/Akt/mTOR pathway in gastric cancer cells, which prevents the growth of cancer cells and promotes cell-protective autophagy as well as in vivo and in vitro apoptosis." (PMID 37298616, 2023). "Through the modulation of the PI3K/AKT/mTOR pathway, miR-451a has the potential to operate as a tumor suppressor in patients with gastric cancer." (PMID 37974228, 2023). "m6A was found to modulate mTOR and PI3K-AKT signaling pathway in many cancer cells, and the hypermethylation-mediated via METTL14 deactivated the PI3K-AKT and mTOR signaling and suppressed gastric cancer cell proliferation and aggression." (PMID 36743697, 2023). "Naringin can also inhibit the expression of mTOR in gastric cancer AGS cells, upregulate the expression of Bad, and downregulate the expression of Bcl xL, resulting in mitochondrial dysfunction, and then promote AGS apoptosis." (PMID 37663256, 2023). "The specific mTOR inhibitor, Rapamycin, can treat gastric cancer combined with other chemotherapy drugs." (PMID 36937439, 2023). "circNRIP1, a widely studied mammalian circRNA, was found to regulate the expression of AKT1/mTOR, by sponging miR-149-5p and promote gastric cancer." (PMID 36841760, 2023). "circNRIP1, a attracted much attention circRNA, was found sponging miR-149-5p to regulate the expression of AKT1/mTOR, thereby promoting gastric cancer." (PMID 36841760, 2023). "Stigmasterol inhibits the proliferation of gastric cancer cells by inhibiting the Akt/mTOR signaling pathway, inducing apoptosis and protective autophagy." (PMID 37109624, 2023). "For example, the combination of corosolic acid and 5Fluorouracil (5FU) more significantly blocked the mammalian target of rapamycin (mTOR) signaling pathway in SNU620 human gastric carcinoma cells and induced apoptosis in these cancer cells." (PMID 37009004, 2023). "For instance, it has been shown that butylidenephthalide caused mitochondria-mediated apoptosis of gastric cancer cells with the upregulated expression regulated in development and DNA damage responses 1 (REDD1) expression and mTOR inhibition." (PMID 35682836, 2022). "This study revealed that HAGLROS can promote tumorigenesis and progression via mTOR signal-mediated inhibition of autophagy in gastric cancer." (PMID 35664787, 2022). "It suggests that evodiamine can act as an AKT/mTOR pathway inhibitor to control apoptosis cell death in evodiamine-treated human gastric cancer cells." (PMID 36135210, 2022). "PI3K/AKT/mTOR signaling pathway dysregulation has been reported to affect gastric cancer prognosis and metastasis through epigenetic alterations, such as DNA methylation and histone modifications." (PMID 35646067, 2022). "LMOD1 was found to regulate the FAK-Akt/mTOR pathway to induce EMT of gastric cancer cells, to further increase invasion and adhesion of gastric cancer cells and promote peritoneal metastasis of gastric cancer cells." (PMID 35488236, 2022). "In conclusion, our results found that LEF1-AS1 and miR-5100 sponge function, and the miR-5100/DEK/AMPK/mTOR axis regulates autophagy and apoptosis in gastric cancer cells." (PMID 35563178, 2022).
gastric cancer (continued). "Salidroside and apolipoprotein C-II induce apoptosis in gastric cancer cells by inhibiting the PI3K/AKT/mTOR signaling pathway, thus inhibiting the progression of gastric cancer." (PMID 36038533, 2022). "Previous studies have shown that Forkhead box D1 antisense RNA 1 (FOXD1-AS1) promotes Forkhead box D1 (FOXD1) translation through PIK3CA/PI3K/AKT/mTOR signaling, thereby aggravating gastric cancer progression and chemotherapy resistance." (PMID 35528617, 2022). "Previous evidence has proposed that Sal B is capable of suppressing EMT to alleviate drug resistance via AKT/mTOR signaling in gastric cancer." (PMID 35502178, 2022). "Interaction between TAMs and gastric cancer cells promoted chemoresistance in gastric cancer via CXCL5/PI3K/AKT/mTOR pathway." (PMID 36151545, 2022). "Cocultures of gastric cancer organoids and immune cells were utilized to study the immunosuppressive function of myeloid-derived suppressor cells (MDSCs), revealing that PD-L1 expression is regulated by the mTOR signaling pathway in gastric cancer." (PMID 35551634, 2022). "(2020) demonstrated that hsa_circ_0010882 played an important role in proliferation, migration, and invasive genotypes of gastric cancer cell lines via regulation of the PI3K/Akt/mTOR signalling pathway." (PMID 35175172, 2022). "Salidroside, a natural active ingredient extracted from Rhodiola rosea, has been shown to decrease the expression of autophagy proteins, suggesting that salidroside induces autophagy through the PI3K/Akt/mTOR pathway in human gastric cancer." (PMID 34976156, 2022). "Here we introduce the PI3K/Akt/mTOR inhibitors which have been under clinical evaluation in other gastrointestinal cancers, including gastric cancer (GC) and colorectal cancer (CRC)." (PMID 35392233, 2022). "The latest study of our group confirmed that TOB1 can induce autophagy in gastric cancer cells via decreasing the activation of AKT/mTOR signaling pathway." (PMID 35465266, 2022). "Previous study has also demonstrated that IGF1R (encoding insulin-like growth factor 1 receptor, IGF-1R), an upstream gene of AKT/mTOR signaling, is a direct target of miR-99b-5p in gastric cancer." (PMID 36077039, 2022). "Studies have shown that PD-L1 expression in gastric cancer regulates the production of c-Myc to promote tumor development through STAT3/mTOR signaling." (PMID 36439438, 2022). "MiR-451 in gastric cancer-derived exosomes can transfer to T cells and activate the mTOR pathway, inducing their differentiation into Th-17 cells." (PMID 36341377, 2022). "In the treatment of gastric cancer, the alkali upregulated the caspase cascade proteins (cleaving PARP, caspase-3, and caspase-9) and inhibited the phosphorylation of Akt/mTOR, resulting in significant apoptosis of human gastric cancer cells." (PMID 35684449, 2022). "The exosomal circNRIP1 sponges miR-149-5p to promote lung metastasis in gastric cancer (GC) via the AKT1/mTOR signaling pathway in patient-derived xenograft mouse models." (PMID 36428785, 2022). "LMOD1 promoted the migration of gastric cancer cells by regulating the FAK-Akt/mTOR pathway in vitro." (PMID 35488236, 2022). "For instance, CSNK2A1 promotes gastric cancer invasiveness via the PI3K-Akt-mTOR signal pathway; CSNK2A1 is a mediator of MEK/ERK inhibitor resistance in KRAS (G12C) mutant LC cells; CSNK2A1 is a promising new prognostic marker for renal cell carcinoma." (PMID 35266446, 2022). "Previous studies indicated that PI3K/AKT/mTOR signal pathway alteration was found in 47% gastric cancer cases." (PMID 35887375, 2022). "Various drugs or compounds have been found to promote apoptosis of gastric cancer cells by inhibiting mTOR in gastric cancer." (PMID 36038533, 2022). "In contrast, when BBR inhibits the MAPK/mTOR/p70-S6K pathway, gastric cancer cell growth is markedly suppressed due to cytostatic autophagy." (PMID 36561763, 2022).
gastric cancer (continued). "LMO4 is an oncogene and was reported to promote the invasion and proliferation of gastric cancer by activating PI3K/Akt/mTOR signalling." (PMID 36347834, 2022). "M2-polarized macrophages inhibited apoptosis and increased 5-FU-resistance by activing the CXCL5/PI3K/AKT/mTOR pathway in gastric cancer cells." (PMID 36151545, 2022). "At present, the therapeutic targets of gastric cancer mainly include HER-2, EGFR, PI3K, mTOR and c-Met, etc., and targeted drugs targeting these receptors and kinases have achieved certain results in the clinical application of gastric cancer treatment." (PMID 36465346, 2022). "Recently, it has been found that Iso promotes apoptosis of gastric cancer MKN-45 cells in a hypoxic environment by inhibiting PI3K/AKT/mTOR-mediated adaptive autophagy." (PMID 36234962, 2022). "The mTOR pathway inhibitor Torin1 partially restored the promoting role of RPS15A overexpression on the gastric cancer cell proliferation." (PMID 35256584, 2022). "PSMC2 enhanced RPS15A levels by targeting hsa-let-7c-3p, and then activated mTOR pathway, thereby promoting the progression of gastric cancer." (PMID 35256584, 2022). "It was found that ginsenoside Rg3 reduced cisplatin resistance by upregulating miR-429 to inhibit the SOX2 and PI3K/Akt/mTOR signaling axes in gastric cancer treatment." (PMID 35684449, 2022). "IL-8 has been shown to induce PD-L1 expression in gastric cancer cells via c-Myc regulated by STAT3/mTOR signaling activation, resulting in immune escape of tumor cells." (PMID 36185222, 2022). "HAGLROS, as a novel lncRNA, was first reported to promote the malignant phenotype of gastric cancer by sponging miR-100-5p to increase mTOR expression and interacting with mTORC1 components to activate the mTORC1 signalling pathway." (PMID 35664787, 2022). "Previous findings also illustrated the apoptosis activation role of SS via inhibiting the Akt/mTOR pathway in gastric cancer (GC) and suggesting the potential anticancer effect of SS in GC treatment." (PMID 35725497, 2022). "They found that this overexpression promoted the proliferation, migration, and invasiveness of gastric cancer cell lines via activating the PI3K/Akt/mTOR flux." (PMID 35090496, 2022). "One multi-omics study demonstrated that mTOR and PI3K-AKI axis were involved in gastric cancer immunity, and the related mutations were associated with better survival of patients with anti-PD-1/PD-L1 immunotherapy." (PMID 35642038, 2022). "9-Demethylmucroniferanine A, Tibetan Medicine Corydalis hendersonii Hemsl-derived bioactive compound, triggers apoptosis in gastric cancer cells by suppressing PI3K/AKT/mTOR and topoisomerase I." (PMID 36139919, 2022). "In a study of gastric cancer, BBR is validated to increase cellular apoptosis, blocks PI3K/AKT/mTOR, and causes the dephosphorylation of the AKT and p38 pathways." (PMID 36561763, 2022). "Overexpressed CYP2E1 was shown to enhance the proliferation as well as invasion of MGC-803 gastric cancer cells and inhibits their apoptosis while up-regulating the levels of intracellular p-Akt, p-mTOR and p-P70S6K." (PMID 36313348, 2022). "The FAK/AKT/mTOR signaling pathway is frequently hyperactivated in various cancers, including gastric cancer." (PMID 36135210, 2022). "Our study also found many patients with clonal pathogenic mutations in the RAS/RAF pathway gene KRAS and the PI3K/MTOR/AKT pathway gene PIK3CA, providing further evidence of their importance in gastric cancer biology." (PMID 36970058, 2022). "The effects of statins and ILF3 on PI3K/AKT/mTOR signaling pathway, cell proliferation, cell cycle, migration and invasion of gastric cancer cells were investigated with Edu assay, flow cytometry and transwell assay." (PMID 35507914, 2022). "Sal-B also regulates proliferation, EMT, and apoptosis to reduce the resistance to DDP via the AKT/mTOR pathway in DDP-resistant gastric cancer cells." (PMID 36386172, 2022).